TIMP3 (TIMP metallopeptidase inhibitor 3)
Diseases named in the same sentence as TIMP3 in open-access papers (continued):
Sharing a sentence is not in itself a finding about the gene and the disease.
cancer (continued). "If cancers having invasive and metastatic ability do not express TIMP-3, preserving or increasing expression of TIMP-3 may lead to a novel cancer therapy." (PMID 15467768, 2004). "We suggest that the lack of TIMP-3 mRNA expression in host stromal tissues ahead of poorly differentiated carcinomas may contribute to their increased invasiveness." (PMID 9184186, 1997). "In the present study, we further detected the protein level of TIMPs in human LoVo cancer cells that had been exposed to PGE2, which demonstrated that PGE2 treatment shows no influence on regulating TIMP-1, TIMP-2, TIMP-3 and TIMP-4." (PMID 21859479, 2011). "No prior study has shown an effect of HMGB1 on MMP-2 and TIMP-3 whereas it has been recently reported that HMGB1 enhances MMP-9 expression in neurons, via Toll-Like Receptor 4 signaling, and in cancer cells via NF-κB signalling." (PMID 21731608, 2011). "SNAIL leads to the induction of TIMP-3, and similarly, although independent of the metalloproteinase inhibitory function, the expression of TIMP-1 induces TWIST1 to negatively regulate E-cadherin in cancer cells, while TIMP2 upregulates this cadherin." (PMID 33419373, 2020).
infection (15 papers, 2009 to 2023). The state of being infected such as from the introduction of a foreign agent such as serum, vaccine, antigenic substance or organism. "This regulation seemed to be directly linked to deficiency of Timp3, as infection of these cells with TIMP3 adenovirus promptly decreased STAT1 mRNA and protein expression to control levels." (PMID 23401241, 2013). "Robust changes in expression of several genes was evident 7 days post-infection; expression of Col1a1, Col1a2, Col3a1, Mmp2, Mmp9 and Lox was significantly increased while expression of Timp3 was significantly decreased." (PMID 24950301, 2014). "The therapeutic capacity of the vectors was compared by measuring smooth muscle cell metabolic activity and migration following infection with vectors that over-express the candidate therapeutic gene tissue inhibitor of matrix metalloproteinase-3 (TIMP-3)." (PMID 23937994, 2013). "Both features were promptly reversed by infection of these cells with a Timp3 adenovirus." (PMID 23401241, 2013). "In the present study, AKT1 was upregulated and TIMP3 downregulated at 48 hpi to various degrees following MDV and REV coinfection comparison to a single infection." (PMID 35392111, 2022). "Infection significantly increased the expression of ACE2, TMPRSS2, ADAM17, TGFB1, CTGF, VEGFA and FN1 but resulted in trends towards decreases in TIMP3 (p = 0.083) and AGF (p = 0.086) in A549 cells compared to control cells." (PMID 32664949, 2020). "Previous study has revealed that TIMP-3 was greatly decreased in in-vitro human monocyte infection models but not at the tissue site." (PMID 32218787, 2020). "Higher collagen deposition after infection in Cyb5r3 SPC–KO mice was accompanied by significantly higher transcript levels of Mmp12, Mmp13, Mmp14, and tissue inhibitor of metalloproteinases 1 (Timp1) but neither Timp2 nor Timp3." (PMID 36749633, 2023). "Thus, filarial lymphedema with or without active infection is characterized by elevated levels of circulating TIMP-1 and TIMP-2 and decreased levels of TIMP-3." (PMID 22679524, 2012).
cardiovascular diseases (12 papers, 2017 to 2025). "TIMP3 levels are mostly decreased in patients with cardiovascular conditions and deficiency of TIMP3 causes or exacerbates cardiovascular diseases partly mediated by elevated proteolytic activities (MMPs, ADAMs, and ADAMTSs)." (PMID 32612540, 2020). "TIMP3 is increased in several cardiovascular diseases, while uncontrollable expression of VEGF‐A (similar to neovascular AMD) has been linked to higher risk and worsened severity of cardiovascular diseases." (PMID 39757747, 2025). "TIMP3 was reduced in various cardiovascular diseases, and study had shown that TIMP3 replenishment ameliorates the disease, suggesting a therapeutic potential for TIMP3 in cardiovascular diseases." (PMID 38145212, 2023). "So far, most functions of TIMP3 in cardiovascular diseases are mediated primarily by its MMP-inhibitive effect and partly by its anti-inflammatory role." (PMID 37057103, 2023). "TIMP3 levels are reduced in various cardiovascular diseases, and studies have shown that TIMP3 replenishment ameliorates the disease, suggesting a therapeutic potential for TIMP3 in cardiovascular diseases." (PMID 32612540, 2020). "Here, we will summarize the reports on the role of TIMP3 in cardiovascular diseases and its potential as a therapeutic factor." (PMID 32612540, 2020). "Additionally, studies have indicated improvement in the disease condition has been achieved by TIMP3 replenishment, suggesting a putative role of TIMP3 in cardiovascular diseases." (PMID 37189744, 2023). "Reduction in TIMP3 levels is observed in various cardiovascular diseases." (PMID 37189744, 2023). "Therefore, it will be valuable to compile the knowledge and advances in TIMP3 structure and function which will support the basis for further investigations in understanding its clinical application in cardiovascular diseases." (PMID 32612540, 2020).
adenocarcinoma (7 papers, 1997 to 2025). A common cancer characterized by the presence of malignant glandular cells. "Furthermore, TIMP-3 expression decreases at the invasive edge of poorly differentiated adenocarcinoma of the human colon, which suggests that a regional loss of TIMP-3 may contribute to their increased invasiveness." (PMID 15467768, 2004). "Methylation rates for ID4, DCL1, BNIP3, H2AFX, CACNA1G and TIMP3 were significantly different between squamous and adenocarcinomas." (PMID 20849603, 2010). "Statistically significantly different methylation rates were observed for ID4-2 (p = 0.011), DCL1 (p = 0.019), BNIP3 (p = 0.003), H2AFX (p = 0.001), H2AFX-2 (p = 0.005), CACNA1G (p = 0.007) and TIMP3 (p = 0.021) when comparing squamous versus adenocarcinoma cases." (PMID 20849603, 2010). "When examining the mammary glands of PyMT Timp3+/+ end-point mice, we consistently noted that all glands were overcome by aggressive adenocarcinomas, but this was not the case in PyMT Timp3−⁄− glands that still contained areas of normal mammary duct." (PMID 25807548, 2015).
kidney disease (6 papers, 2013 to 2024). "Proteins linked to kidney diseases, including heat shock protein family B (small) member 1 (HSPB1), S100A6, transgelin (TAGLN), and TIMP metallopeptidase inhibitor 3 (TIMP3), were shown to be enriched in the proteome unique to AL." (PMID 38892061, 2024). "TIMP3 is the most highly expressed TIMP in the kidney and has a broad protease inhibition profile; its loss associates with age-related renal fibrosis and tubulointerstitial fibrosis, which are important prognostic markers in wide variety of kidney diseases." (PMID 34181080, 2021). "Loss of TIMP3, the only known physiological inhibitors of ADAM17, is associated with age-related renal fibrosis and tubulointerstitial fibrosis, which are important prognostic marker in a wide variety of kidney diseases." (PMID 23401241, 2013). "This evidence further proves that the balance between TIMP-3 and ADAM17 is essential to maintain the physiological function of the kidneys and alterations of such a balance lead to kidney disease." (PMID 35207132, 2022). "TIMP-3 is the most expressed TIMP in the kidneys, and its levels are increased in patients with kidney disease." (PMID 35207132, 2022).
metabolic disorders (6 papers, 2014 to 2025). "Given that TIMP-3 deficiency increases energy expenditure, TIMP-3 may present a novel therapeutic target for preventing metabolic disorders." (PMID 24736588, 2014). "The role of TIMP-3 in controlling metabolism and in the pathogenesis of metabolic disorders has been well documented." (PMID 35207132, 2022). "However, TIMP3 overexpression can alleviate oxidative stress and inflammation in metabolic disorders." (PMID 40893347, 2025). "However, the roles of TIMP-3 in thermogenesis and metabolism, which influence energy expenditure and can lead to the development of metabolic disorders when dysregulated, are poorly understood." (PMID 24736588, 2014). "TIMP-3 may thus present a novel therapeutic target for preventing metabolic disorders." (PMID 24736588, 2014). "miR-877-5p functions as an oncogenic miRNA in TNBC and metabolic disorders by targeting genes such as IGF2 and TIMP3, promoting proliferation and invasion." (PMID 41009685, 2025).
retinopathies (6 papers, 2017 to 2024). "However, recent findings do not fully support the prevailing hypothesis that a gain of function through the dimerisation of mutated TIMP-3 is responsible for retinopathy." (PMID 31877820, 2019). "Besides, inhibition of TIMP3 protected the proliferative retinopathies in mice by inhibiting neovascularization." (PMID 33209201, 2020). "Using human retinal endothelial cells (HREC) exposed to hypoxia and a mouse model of oxygen-induced retinopathy (OIR), we found that TIMP3 expression was significantly decreased at both mRNA and protein levels and this paralleled the activation of STAT3 and up-regulation of miR-21." (PMID 29262585, 2017).
heart disease (5 papers, 2019 to 2023). "Due to the important role of TIMP3 in cardiac structure and function, and the severe adverse outcomes of Timp3-deficiency in heart disease, treatment with TIMP3 could be a potential therapeutic method in these diseases." (PMID 32612540, 2020). "Cigarette smoking, a predominant factor for lung tumorigenesis, was reported to decrease TIMP-1, TIMP-2, or TIMP-3 expression in patients with heart disease or NSCLC." (PMID 33126605, 2020). "TIMP2 and TIMP3 are regulators of cardiac remodeling, hypertrophy, and fibrosis in heart disease and can be induced by Ang II." (PMID 31649814, 2019). "In fact, there have been several studies on the application of TIMP3 in heart disease." (PMID 32612540, 2020).
prostate (4 papers, 2011 to 2023). "To further determine the role of TIMP‐3 in inhibiting invasiveness of mAb NJ001‐treated lung AD cells, we developed SPC‐A1 cells with endogenous TIMP‐3 knockdown, using shTIMP‐3." (PMID 32744429, 2020). "In the present study, upregulation of TIMP‐3 expression in mAb NJ001‐treated cells suggests it has a role in suppressing lung AD invasion and metastasis." (PMID 32744429, 2020).
inflammation (2 papers, 2011 to 2021). Aberrant reaction of the microcirculation characterized by movement of fluid and leukocytes from the blood into extravascular tissues. "Mice deficient in the natural inhibitor of TACE -Tissue Inhibitor of Metalloproteinases 3 (TIMP3)- display significantly elevated levels of TNF and severe liver inflammation, highlighting the physiological importance of sTNF as a pro-inflammatory cytokine." (PMID 35264975, 2021).
benign tumours (1 paper, 2022). "Our previous studies have shown that the expression of TIMP-2 and TIMP-3 are significantly higher in high-grade serous ovarian tumours compared to benign tumours of the same origin." (PMID 36585738, 2022).
head and neck tumor (1 paper, 2013). "This analysis revealed that hypermethylation of CCNA1, DAPK, MGMT, SFRP1 and TIMP3 was frequent in head and neck tumor (40-70%)." (PMID 24359512, 2013).
immune system diseases (1 paper, 2018). "DEGs that enriched to “immune system diseases” played critical roles in cell-matrix communication (THY1, LVRN, LUM, TIMP3, SPOCK1, LGALS3BP, FAT2, and SERPINE2) as well as inflammation (IL1R2, CD22, PTGES, TNFSF10, IL2RB, C3, SERPING1, and IL-17RE)." (PMID 30131724, 2018).
reproductive diseases (1 paper, 2024). "Evidence proposed that the dysregulation of STC1, TIMP3, ITGA2, and INHBA is associated with the development of severe reproductive diseases." (PMID 38730500, 2024).
TIMP3 also shares sentences with these, for which no sentence is quoted: lymphoma (5 papers); Doyne honeycomb retinal dystrophy (3); dysplasia (3); neuroblastoma (3); brain tumor (2); cerebral amyloid angiopathy (2); Degenerative Diseases (2); glaucoma (2); Glucose intolerance (2); hereditary retinal degeneration (2); Hyperinsulinemia (2); idiopathic pulmonary fibrosis (2); interstitial nephritis (2); ischaemic stroke (2); ischemia‐reperfusion injuries (2); ischemic cardiomyopathy (2); oral squamous cell carcinoma (2); Oropharyngeal Cancers (2); oropharyngeal squamous cell carcinoma (2); pancreatic ductal adenocarcinoma (2); rheumatoid arthritis (2); small cell lung carcinoma (2); thyroid nodule (2); acanthamoebiasis (1); acute myocardial infarction (1); Aortic dissection (1); aortic valve insufficiency (1); ascending aortic aneurysms (1); atopic asthma (1); autoimmune disease (1).
A further 84 diseases each share a sentence with TIMP3 in 1 paper.